SNORD115-21 (small nucleolar RNA, C/D box 115-21)
Synonyms: HBII-52-21
Gene: Small nucleolar RNA gene on chromosome 15 (25,208,083 to 25,208,163, forward strand). Ensembl gene ENSG00000199833.
Gene Ontology:
Biological process: RNA processing
Cellular component: nucleolus
Homologues: Orthologues: macaque SNORD115 (99% identical). Paralogues in human: SNORD115-40 (100% identical), SNORD115-10 (99% identical), SNORD115-12 (99% identical), SNORD115-13 (99% identical), SNORD115-9 (99% identical), SNORD115-11 (98% identical), SNORD115-14 (98% identical), SNORD115-16 (98% identical), SNORD115-20 (98% identical), SNORD115-29 (98% identical), SNORD115-36 (98% identical), SNORD115-42 (98% identical), and 37 more.